HIF1A (hypoxia inducible factor 1 subunit alpha)
Diseases named in the same sentence as HIF1A in open-access papers (continued):
Sharing a sentence is not in itself a finding about the gene and the disease.
cancer (4,606 papers, 2002 to 2026). A tumor composed of atypical neoplastic, often pleomorphic cells that invade other tissues. "Overexpression of HIF-1α has been linked to poor prognosis in several cancers, including breast, cervical, oropharyngeal, ovarian, and endometrial cancers." (PMID 41526224, 2026). "At the protein level, SIAH2 regulated glycolytic enzymes and WNK1/hypoxia-inducible factor-1α (HIF-1α) signaling, effects that were amplified by cancer-associated fibroblast (CAF)-derived conditioned medium." (PMID 41596707, 2026). "Within the nucleus, PKM2 is a transcriptional coactivator that confers malignant potential to cancer cells through its association with various transcription factors including Oct-4, HIF-1α, β-catenin, and STAT3." (PMID 40059196, 2025). "We believe these findings contribute to a deeper understanding of the molecular mechanisms underlying bone pathology associated with cancer metastasis and warrant further investigation into therapeutic strategies targeting the Hif1α/Hmox1 axis." (PMID 39814705, 2025). "Resistance is mainly caused by metabolic reprogramming, cancer adaptation to its microenvironment, and activation of HIF-1α." (PMID 40076506, 2025). "The upregulation of HIF‐1α and its downstream effects on FAO are often influenced by the genetic landscape of cancer cells, particularly mutations that stabilize HIF‐1α under normoxic conditions." (PMID 40391753, 2025). "TSGA10’s dual association with Complex III (via CytC1) and Complex IV-linked HIF-1α pathways positions it as a critical orchestrator of mitochondrial fidelity, with profound implications for cancer." (PMID 40507237, 2025). "One report showed that cancer cells and endothelial cells supplemented with starvation medium caused an increase in the level of HIF-1α via cap-independent translation initiation." (PMID 40358197, 2025). "Intratumoural hypoxia has been linked to induced HIF-1α overexpression and aggressive, cancer phenotypes." (PMID 39470609, 2025). "Subsequently, cancer-infiltrating macrophages activate HIF-1α, which causes them to secrete IL-23, supporting an inflammatory phenotype." (PMID 40422244, 2025). "GDF6 upregulates the VEGFR/PI3K-Akt pathway, enhancing endothelial cell recruitment and vascularization, and collaborates with HIF-1α to regulate hypoxia responses and recruit cancer-associated fibroblasts (CAFs), fostering an immunosuppressive niche." (PMID 40699648, 2025). "In this study, the authors showed the ataxia telangiectasia mutated (ATM)/AKT/HIF-1α signaling axis plays a key role in the anti-cancer effects of theasaponin E1." (PMID 41373772, 2025). "HIF-1α has been associated with many diseases, including cancer and cardiovascular and inflammatory diseases, and has been studied in a wide variety of cells." (PMID 40168275, 2025). "Sirt3 depletion causes HIF1α stabilization via an increase in reactive oxygen species in cancer cells, whereas HIF1α depletion results in increased expression of Sirt3 in skeletal muscle." (PMID 40308032, 2025). "Downregulation of HIF1/2α in hypoxia condition impairs cancer cell invasion and growth, and HIF1α inhibition in tumour‐associated macrophages can enhance antitumour immunity." (PMID 39866010, 2025). "HIF-1α is a gene that plays a crucial role in cancer and is associated with various biological processe." (PMID 40860815, 2025). "During normal development, HIF-1α regulates many processes, including neurogenesis, angiogenesis, and cell survival, and its dysregulation is linked to a range of cancers." (PMID 40802851, 2025). "Lipid-based nanoparticles that encapsulate HIF-1α siRNA effectively silence the gene associated with hypoxia adaptation in cancer cells." (PMID 40136686, 2025). "An increased availability of hydroxyproline in solid tissue is associated with Hypoxia-inducible factor 1-alpha (HIF1-α) mediated cancer cell survival by promoting expression of matrix metalloproteinase and degradation of the extracellular matrix (ECM)." (PMID 39904853, 2025).
cancer (continued). "In cancer cells, LD accumulation is a hallmark of hypoxia, with HIF-1α acting as a master regulator to sustain cellular homeostasis and survival." (PMID 40783384, 2025). "HIF-1α is a hypoxic marker elevated in several cancers and is associated with poor prognosis and overall survival." (PMID 41373645, 2025). "Elevated levels of hypoxia-inducible factor-1α (HIF-1α) are associated with advanced cancer progression and unfavorable clinical outcomes in LUAD patients." (PMID 40691138, 2025). "In this study, we found that HIF‐1α was highly expressed in the cancer tissues of GC patients and was associated with N stage." (PMID 40954549, 2025). "Stabilization of hypoxia-inducible factor 1 alpha (HIF1α), which plays a pivotal role in regulating cellular responses to insufficient oxygen, is implicated in cancer progression, particularly epithelial-mesenchymal transition and metastatic dissemination." (PMID 40701956, 2025). "Hypoxia is a feature of cancer associated to progression and resistance to therapies, triggering cellular stress and “glycolytic shift” through the activation of HIF-1α." (PMID 40651947, 2025). "WWOX, by tightly regulating HIF1α, is responsible for this mechanism in cancer cells consequently associated with cancer cell proliferation, invasiveness, patients’ survival, and treatment response." (PMID 41007296, 2025). "Increased levels of HIF1α and HIF2α have been associated with poor prognosis in various human cancer types." (PMID 38509584, 2024). "In S-phase tissues, the expression of LAMB3 and HIF1A, associated with pathways in cancer, increased in EMS patients, while the expression of PAM, related to responses to hypoxia, was reduced." (PMID 39408909, 2024). "The expression HIF-1α by cancer-associated fibroblasts is inhibited and degraded by increased levels of p-AMPK activated by MET through the transformation of tumor fibroblasts in the prolyl hydroxylases axis." (PMID 39246697, 2024). "Hypoxia-inducible factor 1-alpha (HIF1A), which is activated by the growth of cancer cells, causes hypoxia and upregulates BNIP3." (PMID 38262996, 2024). "Another reason for the glycolytic shift in cancer is the accumulation of ROS, which causes the activation of HIF-1α." (PMID 38255314, 2024). "It is well-established that the activation of HIF-1α and its associated signaling cascade has been linked to an increase in the migration and invasion of cancer cells." (PMID 38955827, 2024). "Using advanced techniques, researchers found that ZHX2 collaborates with HIF-1α on specific gene promoters, promoting gene expression linked to cancer." (PMID 38396737, 2024). "Higher NOD-like receptor (NLR) family pyrin domain-containing 3 (NLRP3) inflammasome levels in cancer cells are linked with increased HIF-1α expression." (PMID 38904007, 2024). "Among the HIF-1α target genes associated with migration and invasion of cancer cells, our microarray data showed that solute carrier family 2, facilitated glucose transporter member (SLC2A1) mRNA exhibited a significant increase in response to hypoxia." (PMID 39858431, 2024). "A study demonstrated the association of a HIF1A single nucleotide polymorphism (SNP) with the risk of various cancers, but GC was excluded from the meta-analysis." (PMID 38877062, 2024). "Tribbles regulation has been mechanistically linked to hypoxia and HIF-1α in a variety of cancer cells and in Drosophila fat body tissue." (PMID 38896446, 2024). "In cancer-associated fibroblasts (CAFs), HIF-1α mediated extracellular matrix (ECM) remodeling and metabolic reprogramming support cell survival." (PMID 38841361, 2024). "Previous findings in cancer cells have indicated that hypoxia‐induced K63‐polyubiquitinated USP7 deubiquitinates HIF‐1α causing CBP‐mediated H3K56 acetylation on the gene promoter of HIF‐1α to advance epithelial‐to‐mesenchymal transition and metastasis." (PMID 38602256, 2024).
cancer (continued). "Hypoxia-inducible factors (HIFs) are primary regulatory elements responding to hypoxia, with the activation of HIF-1α closely associated with poor prognosis in cancer." (PMID 39049021, 2024). "Dysregulation of HIF-1α signaling can contribute to the development of various pathologies associated with EndMT, such as fibrosis, cancer, and cardiovascular diseases." (PMID 38195914, 2024). "This is probably because M4N induces a negative impact on cancers by its activity that influences a broad range of biological processes as a dual inhibitor of SP1 and HIF1A and makes cancers susceptible to a second anticancer drug." (PMID 39590335, 2024). "Hypoxia in the TME is often associated with cancer cell development and metastasis, with HIF-1α being a pivotal factor in hypoxia adaptation." (PMID 38794281, 2024). "The interaction network of 39 genes thus identified encoding proteins revealed HIF1A as a prominent metastasis target due to its high degree of connectivity and its involvement in cancer-related pathways." (PMID 39458948, 2024). "Clinically, elevated circulating levels of HIF-1α are linked to cellular injury in other disease processes in renal, cardiovascular, and cancer research." (PMID 38547092, 2024). "In particular, we found that CHOL tissues had high levels of hypoxia, a known factor for poor prognosis in cancer, which is associated with increased tissue damage and chronic inflammation, which was most directly associated with HIF1A expression levels." (PMID 40708677, 2024). "HIF-1α dysregulation in NRF2-silenced cancer cells was associated with short non-coding miRNA miR-181c elevation." (PMID 38674143, 2024). "The study also explored the regulatory role of HIF-1α/ERRα in preventing and treating EC, providing new insights into the molecular mechanisms underlying cancer progression." (PMID 38577616, 2024). "This SMURF2-mediated degradation mechanism bypasses the traditional VHL (von Hippel-Lindau) pathway, offering an alternative strategy to control HIF1α levels in cancers where VHL is mutated, such as in renal cell carcinoma." (PMID 39697237, 2024). "This aberrant activation of HIF-1α in cancer cells is due to genetic mutations or epigenetic alterations that disrupt its normal regulation." (PMID 38205087, 2024). "We report a critical role for USP7 in regulation of HIF‐1α mediated VEGF production by cancer‐associated fibroblasts (CAFs) leading to reprograming of the TME." (PMID 38602256, 2024). "Elevated expression of HIF1A is typically associated with increased patient mortality in various cancer types." (PMID 38469312, 2024). "HIF-1a has also been linked to the regulation of various cancer phenotypes such as cell proliferation, metastasis, and angiogenesis." (PMID 38951854, 2024). "The induction of PDK by hypoxia-inducible factor-1 alpha (HIF-1α) has been demonstrated to cause chemotherapy resistance in cancer cells." (PMID 38255882, 2024). "SMURF2 and HIF1α are pivotal regulators in cancer biology, influencing pathways associated with protein degradation, hypoxic response, and cellular adaptation." (PMID 39697237, 2024). "HIF1α is often overexpressed in cancer tissues and associated with patients’ poor clinical prognosis." (PMID 38769340, 2024). "Further, studies demonstrate that CDK4/6 inhibitors, such as palbociclib, synergize with HSP90 inhibitors to reduce HIF1α levels and suppress cancer cell viability, even in Rb-deficient tumors." (PMID 39697237, 2024). "HIF-1α as a key player in cancer metabolism reprogramming, has been closely associated with aerobic glycolysis." (PMID 38577598, 2024).
cancer (continued). "Given its pivotal role in cancer biology, HIF-1α has emerged as a promising target for diagnostic, prognostic and therapeutic purposes, providing a foundation for the development of more effective cancer treatments." (PMID 38339408, 2024). "HIF-1α has been documented to exhibit overexpression in multiple types of cancer and has been implicated in tumor survival by contributing to drug resistance." (PMID 39518022, 2024). "HIF-1α is involved in various biological processes, particularly those associated with various cancer processes, including cell proliferation, apoptosis, angiogenesis, glucose metabolism, and energy metabolism." (PMID 39202223, 2024). "Increasing evidence has shown that the HIF-1α pathway is associated with acquisition of cancer stem-like properties." (PMID 39728923, 2024). "HIF-1α controls gene expression associated with various signaling pathways that promote cancer cell proliferation and survival." (PMID 38766303, 2024). "Upon exposure to the BC cell environment, cancer-associated fibroblasts increase the expression of hypoxia-inducible factor-1α (HIF-1α)." (PMID 39246697, 2024). "Survival data from clinical studies indicate that intratumoral hypoxia and increased Hypoxia Inducible Factor 1 alpha (HIF-1α) expression are associated with aggressive cancers." (PMID 36982940, 2023). "In various types of cancer, HIF-1α expression was reported to be associated with lymphatic metastasis, but the underlying mechanism has not yet been well characterized." (PMID 37841777, 2023). "Owing to the multiple roles of HIF-1α, its activity is associated with various diseases (e.g., inflammatory and metabolic diseases and cancer proliferation and metastasis)." (PMID 36831085, 2023). "On the other hand, the reverse Warburg effect reflects that adjacent cancer cells are metabolically supported by cancer-associated fibroblasts (CAFs), which can undergo HIF-1α-induced autophagosomal degradation and aerobic glycolysis." (PMID 37168255, 2023). "Oncogenic Ras/MEK signaling-induced HIF-1α expression has also been implicated in increasing glycolytic flux and driving cancer progression." (PMID 36768924, 2023). "HIF-1α and Ki-67 expression in the resected lung tissue were representatively increased in the cancer cells from patients with underlying IP." (PMID 38012636, 2023). "In previous studies, HIF-1α was found to be overexpressed in numerous human cancers and multiple cell types, and HIF-1α activity was associated with tumorigenicity and metastasis." (PMID 37747648, 2023). "High expression of HIF1α in cancer tissue is believed to associate with high therapeutic resistance, poor survival and more metastasis in patients." (PMID 35953652, 2023). "Prostate cancer stem cells with a mesenchymal phenotype are triggered by cancer-associated fibroblasts (CAFs) by HIF-1α/β-catenin-dependent signaling pathways." (PMID 37046617, 2023). "HIF-1α activation is important for tumorigenicity and angiogenesis in nude mice; it is overexpressed in human cancers and is associated with angiogenesis induced by tumors and hypoxia." (PMID 36831545, 2023). "The expression of MT4-MMP and HIF-1α in these tumors was associated with poor overall survival of cancer patients." (PMID 37373092, 2023). "HIF-1α, a key gene among hypoxia-induced genes, participates in the metabolic reprogramming of cancer cells in hypoxic and nutrient-deficient environments." (PMID 37864196, 2023). "Along these lines, allicin and diallyl trisulfide suppressed the HIF-1α pathway in cancer and other pathogenic contexts." (PMID 37047205, 2023). "Overexpression of HIF-1α has been found in many gastroenterological cancers, which is implicated in drug resistance and poor prognosis of cancers." (PMID 37333486, 2023). "And HMOX1 was indicated to be associated with HIF-1a gene related cancer hypoxia and oxygen homeostasis regulation." (PMID 37438709, 2023).
cancer (continued). "It has been confirmed that drug resistance is caused by an expansion of both stroma cells and cancer cells, which causes hypoxia due to HIF-1α activation and, therefore, provides a novel target for tumor therapy." (PMID 38136311, 2023). "A recent study found that vesicles with low miR-7641 levels derived from cancer-associated fibroblasts (CAFs) also promoted malignant progression of cancer cells by regulating HIF-1α." (PMID 37204526, 2023). "HIF-1α is overexpressed in many types of cancer and has been linked to the survival and self-renewal of CSCs." (PMID 37886967, 2023). "The well-established regulator of cancer cell physiology, HIF-1α, is also linked with lipid metabolism." (PMID 37256177, 2023). "Some studies have shown that HIF-1α expression is upregulated in superficial OSCC and is associated with the early stage of OSCC transformation and development, suggesting that HIF-1α is a cancer risk marker." (PMID 37095487, 2023). "HIF-1α also regulates the 4-trimethylaminobutyraldehyde dehydrogenase, which is associated with cancer cells metastasis, self-renewal, and resistance in BC." (PMID 37492478, 2023). "PD-L1 is closely associated with ROS, and its elevated membrane expression on cancer cells is associated with high HIF-1α expression." (PMID 37563639, 2023). "HIF1A was positively related to the immune score, stromal score, and ESTIMATE score; indicating that the elevated HIF1A level was linked to a more abundant stromal content in cancer, another potential mechanism by which HIF1A regulated PTC progression." (PMID 36994412, 2023). "The pathway enrichment analysis on the DEAS events regulated by SFs indicated that most pathways were significantly associated with cancer metabolisms, such as hypoxia, HIF1A signaling pathway, and Ribosome." (PMID 37735421, 2023). "In the hypoxic microenvironment of solid tumors, high expression of HIF-1α is associated with poor prognosis in various cancers, including HCC." (PMID 37240068, 2023). "HIF-α stabilization is an early event in the formation of renal lesions which overtime advance to malignant cancers because of multiple secondary events including the loss of the HIF-1α isoform." (PMID 36831657, 2023). "In response to this hypoxia, cancer cells upregulate hypoxia-inducible factor 1-alpha (HIF1α), which causes increased glucose uptake and glycolytic metabolism and a resultant increase in lactate release into the TME." (PMID 35203357, 2022). "Hypoxic conditions are associated with many cancers due to limited oxygen supply, which leads to overexpression of a transcription factor called HIF-1α." (PMID 36153528, 2022). "HIF1A gene polymorphisms have been confirmed the association with cancer risk through the statistical meta-analysis based on single genetic association (SGA) studies." (PMID 35972942, 2022). "Consistently, it was unveiled that specific polymorphisms of HIF-1α are associated with cancer susceptibility and progression." (PMID 35527284, 2022). "In human cancer, it has been indicated that HIF-1α is associated with resistance to radiation therapy." (PMID 36669005, 2022). "HIF-1α is associated with several crucial aspects of cancer progression, including migration, invasion, angiogenesis and chemoresistance." (PMID 36296726, 2022). "Hypoxia-induced HIF-1α is stated to be associated with cancer cell malignancy and chemoradiation therapy resistance." (PMID 35205167, 2022). "And the functional loss of APC caused by APC mutation facilitates cancer cell survival by inducing HIF-1α expresses." (PMID 35928881, 2022). "A hypoxic TME in which HIF-1α is greatly activated stimulates the cancer-associated fibroblasts (CAFs) to release stromal-derived factor-1 (SDF-1), which in turn recruits immature myeloid cells into TME." (PMID 35805044, 2022). "The overexpression of the HIF-1α protein is associated with the development of resistance to chemo- and radiotherapy in multiple types of human cancers." (PMID 36551540, 2022).